SP1 (Sp1 transcription factor)
Diseases named in the same sentence as SP1 in open-access papers (continued):
Sharing a sentence is not in itself a finding about the gene and the disease.
tumor (continued). "The RNA expression of SP1 is significantly higher in LIHC tumor samples (TCGA-LIHC and LIRI-LIHC datasets) and STAD tumor samples (TCGA-STAD dataset)." (PMID 33488678, 2020). "Since SMO‐mediated Hedgehog signalling plays critical roles in tumour occurrence and progression, this study aimed to investigate the regulatory effect of SP1/miR‐326 axis on Hedgehog signalling." (PMID 32743904, 2020). "Specificity protein 1 (SP1)-induced HOXD-AS1 promoted tumor viability, metastasis, EMT, stemness and chemo-resistance in vitro and in vivo by sponging miR-520c-3p to increase oncogene MYCN." (PMID 32857725, 2020). "SP1 plays an important role in the regulation of cell metabolism and cell proliferation, including prominent oncogenes or tumor suppressors." (PMID 32158359, 2020). "Transfection with SP1‐siRNA vector decreased SP1 but increased miR‐326 expression in 143B‐cell‐xenografted tumour, as indicated by the results form PCR assay (P < .001)." (PMID 32743904, 2020). "Sp1 activates the transcriptions of a large number of genes that contain CG-rich promoters and Sp1 target genes play pivotal roles in tumor growth, apoptosis, and tumorigenesis." (PMID 33093451, 2020). "We found that SP1 was commonly overexpressed in RCC tissues compared with that in adjacent non-tumor tissues." (PMID 32432112, 2020). "Targeting NR4A1 by an antagonist leads to the normal expression of Sp1 and redox genes for maintaining low levels of oxidative stress in the tumor microenvironment." (PMID 32050495, 2020). "As a zinc finger transcription factor, Sp1 is an inducer of tumour angiogenesis by directly binding to the VEGF promoter." (PMID 32144747, 2020). "The gene of urokinase receptor (u-PAR) which promotes tumor invasion/metastasis contains Sp1 and Sp3 transcription factor binding sites in the promotor region." (PMID 31075975, 2019). "Numerous literatures have demonstrated that SP1 can promote tumorigenesis, progression and metastasis and its expression level is closely related with tumor invasion and poor prognosis." (PMID 31101117, 2019). "Specificity protein 1(Sp1) is an important transcription factor for regulating tumor growth, and also the binding site of many promoters of apoptosis-related genes." (PMID 31480213, 2019). "Our data establish a clear functional correlation between constitutive activation of the PCP pathway, JNK activity, SP1-mediated RhoU transcription and tumor cell motility." (PMID 30654518, 2019). "Of the 80 paired PDAC tissue, 57 cases showed high expression of SP1, and 23 cases showed low expression; while in the para-tumor samples, 37 cases showed high expression of SP1, and 43 cases showed low expression." (PMID 31101117, 2019). "Herein, we first corroborated the tumor-facilitating role of DLEU1 depended on SP1 through sponging miR-4429." (PMID 31713587, 2019). "Knockdown of SP1/Syncytin1 axis inhibited the progression of NSCLC by the reversion of tumor epithelial‐mesenchymal transition process and suppression of Akt and Erk signaling pathways, suggesting that they are potential targets for targeted therapy of NSCLC." (PMID 31397118, 2019). "It is known that SP1 binds to the GC/CT cassette in the promoter region of the gene, activates the transcription process, and is abnormally expressed in various tumor groups." (PMID 31661799, 2019). "Consistent with inhibition of Sp1, oleacein triggered upregulation of tumor suppressive miRNAs, namely miR-29b and miR-22, which are known to be negatively regulated by this transcription factor." (PMID 31315220, 2019). "The expression of SP1 protein in tumor tissues of the SP1 rs1353058818 locus DD genotype was significantly higher than in tissues of the ID type, and in tissues of type II it was the lowest." (PMID 31270251, 2019). "Univariate and multivariate analyses showed that tumor differentiation and co-expression of SP1 and LOXL2 were independent factors for disease-free survival." (PMID 30976063, 2019).
tumor (continued). "Specificity protein 1 (SP1), a transcription factor, has been demonstrated to play a critical role in the regulation of tumor-associated genes required for tumor survival, progression and metastasis." (PMID 30474556, 2018). "Western blotting results showed Sp1 overexpression increased Bak expression both in liver immortal non-tumour cells and HCC cells." (PMID 29653560, 2018). "The correlation between the NCK1-AS1 expression and these transcription factors E2F1, XBP1 and SP1 were performed and correlation analysis revealed that NCK1-AS1 has a significantly positive correlation with SP1 in TCGA CESC Tumor data set." (PMID 29416014, 2018). "The expression status of SP1-TINCR-miR-7-KLF4 was further characterized in xenograft tumor at both transcriptional and translational level, which definitely consolidated our in vitro observations." (PMID 29614984, 2018). "The role that microglia plays in GBM tumor progression was verified by the identification of protumorigenic Osteoactivin (GPNMB) and Osteopontin (SP1) expression in profiled GBM tumor-associated microglia." (PMID 28299344, 2017). "Concordantly, TFF3 expression in EC tumour samples positively correlated with the levels of SP1, and the activity and levels of phospho c-JUN." (PMID 29100386, 2017). "It has been reported that Sp1 is an essential transcription factor for multiple genes that are key to the regulation of physiological process and tumor development and progression." (PMID 28117748, 2017). "In CRC, activation of Sp1 often positively correlates with tumor malignancy and indicates poor prognosis." (PMID 28422727, 2017). "Sp1 has been reported to regulate many biological functions, including cell growth, differentiation, survival, tumor progression, and metastasis." (PMID 28484232, 2017). "The binding site of SP1 had higher enrichment in the upstream regulation region of 17P13.3 and 17P13.1 and the upstream regulation region of the 8 tumor suppressor genes all found SP1 binding site." (PMID 28473981, 2017). "Transcription factor Specificity protein 1 (Sp1) plays a role in promoting oncogenes required for tumor survival, metastasis and progression." (PMID 28894282, 2017). "Among these candidates, Sp1 was identified as a potential target of miR-22 and selected for further analysis, as it is an important oncogene which is up-regulated in several tumor types." (PMID 28422727, 2017). "Although Sp1 regulates tumorigenesis by affecting several cellular processes, the role of Sp1 in tumor metabolism, especially in steroidogenesis, remains poorly understood." (PMID 28530704, 2017). "The results showed that in tumor tissues, miR-29c expression was down-regulated while SP1 and MGMT mRNA expression was up-regulated as compared with in PTBE tissues." (PMID 28831025, 2017). "Since Nm23-H1 has been considered as a tumor metastasis suppressor, first, we studied the role of Nm23-H1 in the regulation of Sp1 and hnRNPA2/B1 levels." (PMID 28831131, 2017). "The mice treated with miR-29c mimics had decreased Sp1/ TGF-β1 expression in tumor tissue and showed a delayed tumor growth with less tumor volume than that treated with PBS or negative control." (PMID 27829234, 2016). "Our previous studies showed that sulfatide promotes cell adhesion to vitronectin and metastasis of tumor cells in HCC via modulation of integrin αV subunit expression by phosphorylated transcriptional factor Sp1(specificity protein 1) and miR-223." (PMID 27145276, 2016).
tumor (continued). "Of 60 paired HCC samples, 70% showed a significant increase (from 1.1‐ to 3.6‐fold) in Sp1 protein expression in the tumor cells." (PMID 26763486, 2016). "Sp1 in 42/45 tumor tissues and Nanog in 44/45 tumor tissues were evidently evaluated than these in corresponding para-tumor tissues when analyzed by IHC." (PMID 27685621, 2016). "Meanwhile, a positive correlation between Sp1 and Nanog in tumor tissues was found (r=0.324, P=0.03)." (PMID 27685621, 2016). "Compared with the matched nontumor part, 42 (70%) paired HCCs showed an increase (from 1.1‐ to 3.6‐fold) in Sp1 protein expression in the tumor cells (P < 0.001)." (PMID 26763486, 2016). "Collectively, it was suggested that the upregulated expression of COX2 by Sp1 in PDAC cells promotes tumor cell epithelial–mesenchymal transition and facilitates their migration and metastasis into lymphatic vessels." (PMID 27057636, 2016). "Whereas, the treatment of miR-29c inhibitor promote the tumor progression with enhanced of Sp1/ TGF-β1 expression." (PMID 27829234, 2016). "Other tumor suppressor gene VHL, Von Hippel–Lindau tumor suppressor also inhibits IGF1R promoter activity through interaction with Sp1 protein." (PMID 27405474, 2016). "A study based on 396 gastric tissue samples confirmed that the expression of Sp1 increases with tumor progression." (PMID 26511642, 2016). "SP1 transcription factor expression levels remained relatively unchanged after treatment in both normal and tumor cells." (PMID 27727290, 2016). "Inhibition or knocking down of Sp1 to normal cellular level has been reported to decrease tumor formation, growth and metastasis." (PMID 25816367, 2015). "As shown by the luciferase assay, NZ28 inhibited not only the transcriptional activity of HSF1 but also that of NF-κB and Sp1 in H1339 and T47D tumor cells." (PMID 25854583, 2015). "Together with our corroboration of the dominant role of Sp1, the findings support the rationale of targeting this transcription factor to inhibit tumour progression." (PMID 26448047, 2015). "We also provide evidence that inhibition of Sp1 activation coupled with ERβ activation with 2-ME2 suppresses tumor cell growth and induces apoptosis." (PMID 25816367, 2015). "In conclusion, our results demonstrate that specific knockdown of KV9.3 decreased cell viability through G0/G1 cell cycle arrest and tumor growth in vivo, and implicate Sp1 in regulating the expression of KV9.3 in HCT15 and A549 cells." (PMID 25924237, 2015). "Further experiments will be needed in order to confirm that Sp1-mediated inflammatory gene expression is relevant in the context of a tumor microenvironment." (PMID 25738304, 2015). "While the overexpression of SP1 protein contributes to metastasis in diverse tumour types, its inhibition in colorectal CSC has been shown to markedly suppress CSC growth and induce apoptosis, which can be achieved by treating the cells with curcumin." (PMID 26457069, 2015). "MTA is a DNA-binding drug that shows preference for G/C-rich DNA sequences, and, therefore, a significant part of the anti-tumor activity of MTA is thought to be mediated by the blockade of the binding of transcription factors such as Sp1." (PMID 26536461, 2015). "The two downstream targets of miR-22, SP1 transcription factor (SP1) and oestrogen receptor 1 (ESR1), are implicated in promoting tumour development." (PMID 26457069, 2015).
tumor (continued). "The results of this study highlight the paramount role of Sp1 in driving hAR expression in PCa cells and, therefore, the appropriateness of targeting Sp1 as a means of suppressing tumour progression." (PMID 26448047, 2015). "Sp1 regulates several cellular functions and influences tumor growth by controlling expression of genes related to tumor growth and development such as cyclin D1, c-Jun, and c-Myc34." (PMID 25418289, 2014). "KLF4 acts as cell cycle regulator and functions as a tumor suppressor through its ability to induce p21CIP and suppress SP1 expression." (PMID 25037230, 2014). "In tumor tissue samples, two Sp1 expression patterns, i.e. high and low Sp1 expression, were identified." (PMID 24519909, 2014). "Several studies have recognized that the expression levels of transcription factor Sp1 dramatically increases during transformation, representing a critical effect in tumor development or maintenance." (PMID 24423061, 2014). "Transcription factor Sp1 is multifaceted, with the ability to function as an oncogene or a tumor suppressor, depending on the cellular context." (PMID 25099028, 2014). "A significant reduction in tumor-driven cord formation, VEGF secretion, and in vivo tumor angiogenesis was observed upon SP1 knockdown." (PMID 24759702, 2014). "We observed significant inhibition of Sp1 expression in tumor xenografts from Mith-treated mice compared with control mice." (PMID 25418289, 2014). "Sp1 was expressed predominantly in the nuclei of NPC cells of the tumor regions (T), but demonstrated weak signal in the NPEC of the non-tumor regions (N)." (PMID 25099028, 2014). "It is known that the 309G variant is enhancing the binding of Sp1 transcription factor to its promoter, increasing therefore MDM2 expression and accelerating tumor formation." (PMID 24708820, 2014). "The authors also identified CDK6, SIRT1 and Sp1 as miR-22 targets and postulated that miR-22 act as tumor suppressor." (PMID 22538858, 2013). "The immunochemical analysis of SP1 revealed a significant increase in its expression during tumor progression (p<0.0001)." (PMID 23437057, 2013). "Sp-1 is mostly influenced by transcription factor that activates many genes containing GC box in their promoters involved in tumor progression." (PMID 23970932, 2013). "The most significant factors were tumor size and pathological stage in both subtypes, and SP1 expression exhibited a considerable significance in univariate Cox analysis." (PMID 23437057, 2013). "Several reports have referred to a correlation between Sp1 and Sp3 and tumor development, growth and metastasis." (PMID 23326307, 2013). "Accordingly, inhibition of Sp1 or its knock-down to normal cellular levels usually decreases tumor formation, growth, and metastasis." (PMID 23028678, 2012). "Sp1 expression levels increase during transformation, which can play a critical role in tumor development or maintenance." (PMID 22734486, 2012). "For some time Sp1 protein expression was believed to be a critical factor in tumor development, growth and metastasis, but other studies argue that its over-expression is detrimental to various cells." (PMID 23300749, 2012). "Two Sp-factor binding sites are located in the GC-rich box of MDR1, however studies in epithelial cells and tumours indicated that it is Sp1 that targets this site." (PMID 23133566, 2012). "Tumor lysates from control and treated animals were analyzed by western blot analysis for Sp1, Sp3 and Sp4, and levels were quantitated relative to β-actin and showed significant decreases in expression of Sp1, Sp3 and Sp4 in aspirin vs. control animals." (PMID 23110215, 2012). "COX inhibitors are also known to alter Sp1 phosphorylation and lead to arrested cell growth in tumor cells, and PGE2 can stimulate cell growth through induction of Sp1 DNA-binding activity." (PMID 22997489, 2012).
tumor (continued). "Numerous studies have documented that the levels of transcription factor Sp1 expression dramatically increased during transformation, indicating a critical influence in tumor development or maintenance." (PMID 22734486, 2012). "This demonstrates that, for BA and possibly other drugs that downregulate Sp1, Sp3, Sp4 and Sp-regulated genes, the pathways required for this response are variable and dependent not only on tumor type but also cell context within the same tumor." (PMID 21864401, 2011). "In vitro studies showed that a core region of hTERT containing two E boxes and several Sp1 sites is sufficient for the major tumor-selective promoter activity." (PMID 20085660, 2010). "Our results suggest that Enz has a major role in downregulating the u-PAR through Sp1/Sp3 and c-Jun(AP-1), besides HIF1α and VEGFC that are implicated in tumour growth and metastasis, in parallel to upregulating tumour-suppressors relevant for NSCLC." (PMID 20736951, 2010). "SP1 is a zinc finger transcription factor important in the regulation of genes involved in cell survival, growth and differentiation, and tumor development and progression." (PMID 20576088, 2010). "In contrast, expressing the transcriptional co-activator Yorkie (Yki), a downstream component of the Hippo tumor suppressor pathway, was able to rescue the growth of Df(btd,Sp1) clones, both in the leg imaginal disc and the adult leg." (PMID 20585625, 2010). "Many strategies including CRCA have been developed using the hTERT core promoter, containing two E boxes and several Sp1 sites, to selectively target tumor cells." (PMID 20085660, 2010). "In primary pancreatic adenocarcinoma Sp1 overexpression identifies advanced stage tumours and predicts a poor clinical outcome." (PMID 19753117, 2009). "We have not included this observation as it is clear intuitively that its effect should drive up the expression of active Sp1 and hence the level of growth factor over what we already have computed in the regions where tumor cells are present." (PMID 19458766, 2007). "A possible proposal is that Sp1 elements protect a CpG island from de novo methylation, occurred in tumor genesis and this needs to be further investigated." (PMID 18053161, 2007). "In the present study, we showed that treatment with TMZ inhibited telomerase activity in TMZ-sensitive tumour cells by interfering with binding sites of transcription factor Sp1." (PMID 12942127, 2003). "Gene networks that sustain tumor-cell plasticity and invasion are described, including EMT-linked transcription factors such as SNAIL and TWIST, as well as broader transcriptional regulators like SP1." (PMID 41596524, 2026). "Moreover, analysis of the Clinical Proteomic Tumor Analysis Consortium and Gene Expression Omnibus databases indicated that SP1 expression was higher in colorectal LM tissues than in NATs or primary tumor tissues." (PMID 41017455, 2025). "The depletion of SP1 or pharmacologic inhibition of the ACSS2–SP1–SAT1 axis could diminish the tumor burden." (PMID 40399304, 2025). "Both YAP and SP1 play vital roles in tumorigenesis and tumor progression." (PMID 39875519, 2025). "Furthermore, we employed KPC mice to mimic PanIN‐to‐PDAC progression, wherein genetic ablation of SP1 suppressed tumor development." (PMID 40832790, 2025). "Lactate plays a key role in maintaining stem cell characteristics by upregulating the transcription factor SP1 (Specificity Protein 1), which, in turn, enhances tumor aggressiveness, invasiveness, and immune evasion via sterol regulatory element-binding protein 1 (SREBP1)." (PMID 40422220, 2025).